FGD3 (FYVE, RhoGEF and PH domain containing 3)
Description:
Promotes the formation of filopodia. May activate CDC42, a member of the Ras-like family of Rho- and Rac proteins, by exchanging bound GDP for free GTP. Plays a role in regulating the actin cytoskeleton and cell shape (By similarity).
Synonyms: ZFYVE5; FLJ00004
Tractability: PROTAC: ubiquitination databases record sites on it; its protein half-life has been measured.
Gene: Protein-coding gene on chromosome 9 (92,947,486 to 93,036,238, forward strand). Ensembl gene ENSG00000127084.
Subcellular location: Cytoplasm; Cytoplasm, cytoskeleton
Subcellular location (Human Protein Atlas): Cytosol; Nucleoplasm
Pathways (Reactome):
Signal Transduction: CDC42 GTPase cycle; G alpha (12/13) signalling events; NRAGE signals death through JNK
Gene Ontology:
Molecular function: guanyl-nucleotide exchange factor activity; small GTPase binding; metal ion binding
Biological process: actin cytoskeleton organization; cytoskeleton organization; filopodium assembly; regulation of cell shape; regulation of GTPase activity; regulation of small GTPase mediated signal transduction
Cellular component: cytoplasm; cytosol; Golgi apparatus; lamellipodium; ruffle; cytoskeleton
Genetic constraint (gnomAD): Loss-of-function variants: 45 observed, 71.6 expected, observed/expected ratio (o/e) 0.63, 90% interval 0.49 to 0.81. The upper end of that interval is the gene's LOEUF score, 0.81, which puts it in group 3 of 6, group 1 being the genes least tolerant of losing a copy. Missense variants: 829 observed, 958.33 expected, observed/expected ratio (o/e) 0.87, 90% interval 0.82 to 0.92. Synonymous variants: 368 observed, 396.42 expected, observed/expected ratio (o/e) 0.93, 90% interval 0.85 to 1.01.
Homologues: Orthologues: chimpanzee FGD3 (99% identical), macaque FGD3 (95% identical), guinea pig FGD3 (77% identical), rabbit FGD3 (75% identical), pig FGD3 (75% identical), mouse Fgd3 (75% identical), rat Fgd3 (75% identical), dog FGD3 (72% identical), Caenorhabditis elegans exc-5 (24% identical), Caenorhabditis elegans frm-3 (8% identical). Paralogues in human: FGD1 (46% identical), FGD4 (40% identical), FGD2 (34% identical), FGD6 (25% identical), FGD5 (22% identical), FARP2 (20% identical), FARP1 (18% identical), ECT2L (12% identical), ARHGEF39 (11% identical), FRMD7 (6% identical).
Diseases named in the same sentence as FGD3 in open-access papers:
FGD3 is named in the same sentence as 24 diseases in open-access papers, as found by Europe PMC text mining. Sharing a sentence is not in itself a finding about the gene and the disease. The quoted sentences say what the papers report.
breast carcinoma (10 papers, 2017 to 2025). "FGD3 was reported to be associated with six distinct breast cancer cohorts and four TCGA cancer cohorts and was proposed as an important clinical biomarker for cancers." (PMID 31552087, 2019). "FGD3 is implicated in breast cancer and ARHGAP4 in ovarian tumors." (PMID 30704450, 2019). "Supporting clinical relevance, database analysis shows a strong positive correlation between FGD3 level and a favorable response to chemotherapy in breast cancer patients." (PMID 41225536, 2025). "Although the analysis of TCGA and online KM Plotter showed FGD3 is highly expressed in breast cancer and several other cancers and is a favorable prognostic marker, it has been little studied." (PMID 41225536, 2025). "Since development of resistance to chemotherapy is nearly universal in the metastatic setting, in breast cancer patients with high FGD3 levels, chemotherapy is better able to induce lytic cell death." (PMID 41225536, 2025). "Our data provides a different perspective to potentially explain why FGD3 is a favorable prognostic marker in breast cancer." (PMID 41225536, 2025). "To explore the relevance of our findings in models that were more clinically relevant, we next investigated the role of FGD3 in the response to doxorubicin and ErSO in two breast cancer patient-derived organoids (PDOs), S021 and S035." (PMID 41225536, 2025). "Taken together, we conclude that when breast cancer cells experience cell swelling and osmotic stress, FGD3 activates Cdc42 and then ARP2/3 to induce lamellipodium formation at the cell border and loss of the internal stress fiber network." (PMID 41225536, 2025). "With the strong correlation between FGD3 level and a favorable response to chemotherapy, FGD3 level can be used to identify breast cancer patients most likely to benefit from doxorubicin and other chemotherapy agents that induce lytic cell death." (PMID 41225536, 2025). "Since FGD3 expression is highly elevated in breast cancer, here we focus on its role in breast cancer." (PMID 41225536, 2025). "The impact of FGD3 levels on efficacy of widely used doxorubicin led us to explore the potential of FGD3 as a biomarker for identification of breast cancer patients most likely to benefit from chemotherapy." (PMID 41225536, 2025). "FGD3 is highly expressed in breast cancer as a favorable prognostic marker, but its role in breast cancer is largely unstudied." (PMID 41225536, 2025). "Although the correlation between NINJ1 level in breast cancer and chemotherapy response was much weaker than that of FGD3, it was nonetheless significant." (PMID 41225536, 2025). "FGD3 mainly exists in breast cancer and is a promising biomarker of better prognoses for breast cancer patients." (PMID 36530971, 2022). "Although large scale studies on this biomarker as prognostic factor in breast cancer already exist, further studies are warranted to confirm the role of IHC determination of FGD3 expression as prognostic factor in breast cancer patients." (PMID 34359725, 2021). "The aims of the current study were to extend the analysis of FGD3 gene expression by IHC to a series of breast cancer patients at all age treated at our institution and to compare the effectiveness of FGD3 expression to that of traditional prognostic factors." (PMID 34359725, 2021). "A previous study by our group described the role of FGD3 gene as a significant and independent prognostic factor in young women with breast cancer." (PMID 34359725, 2021). "The most promising one seems to be the FGD3 gene expression, which has been shown to be prognostic in breast cancer: the aim of our study was to analyze the prognostic value of FGD3 expression by immunohistochemistry and to compare it with traditional factors." (PMID 34359725, 2021). "Among new prognostic factors for breast cancer, the most promising one seems to be FGD3 (Facio-Genital Dysplasia 3) gene, whose expression improves outcome by inhibiting cell migration." (PMID 34359725, 2021).
breast carcinoma (continued). "Our results suggest FGD3 to be a significant independent prognostic factor in young breast cancer patients in terms of disease-free survival and overall survival." (PMID 31645624, 2019). "No studies so far have specifically investigated the role of FGD3 in young patients with breast cancer." (PMID 31645624, 2019). "In this study, we analysed for the first time the prognostic role of FGD3 in young breast cancer patients." (PMID 31645624, 2019). "The current study was undertaken to test the prognostic value of FGD3 expression in a young breast cancer population." (PMID 31645624, 2019). "We studied the relationship between traditional prognostic factors, FGD3 expression and outcome in ≤40 years breast cancer patients." (PMID 31645624, 2019). "For this purpose, we analysed and compared the prognostic significance of traditional prognostic factors and FGD3 expression in our series of young breast cancer patients in terms of disease-free survival (DFS) and overall survival (OS)." (PMID 31645624, 2019). "Exploratory analysis of 20,464 single-gene messenger RNAs (mRNAs) in the Molecular Taxonomy of Breast Cancer International Consortium (METABRIC) discovery cohort indicates that low expression of FGD3 mRNA is prognostic for poor outcome." (PMID 32913979, 2017). "Minimal research has focused on it as a possible driver of metastasis in breast cancer, and a pan-cancer analysis in TCGA cohorts found that FGD3 mRNA was a putative prognostic biomarker in other cancers." (PMID 32913979, 2017). "ESR1 transcriptional regulation of FGD3 mRNA expression in the breast cancer cell line ZR-75-1 was confirmed." (PMID 32913979, 2017). "FGD3 mRNA expression was prognostic in each of the HAS breast cancer–defined PAM50 subtypes in which high expression indicated favorable outcome." (PMID 32913979, 2017). "FGD3 protein expression was evaluated in breast cancer tissue microarrays (TMAs) as an indicator of regional lymph node status." (PMID 32913979, 2017). "IHC data from breast cancer TMAs indicates that FGD3 protein expression is a feature of the tumor, and low expression indicates a higher chance of cell migration to lymph nodes." (PMID 32913979, 2017). "FGD3 mRNA is regulated by ESR1 and is associated with favorable outcome in six distinct breast cancer cohorts and four TCGA cancer cohorts." (PMID 32913979, 2017). "Given the potential role of FGD3 in cell migration, it is clearly prognostic in a large collection of breast cancer and other cancer cohorts and has a wide range of treatment options." (PMID 32913979, 2017). "Notably, in an automated Trypan Blue exclusion assay for cell viability, FGD3 overexpression strongly increased the breast cancer cells sensitivity to ErSO, while FGD3 knockout rendered the cells resistant to ErSO-induced rapid cell death." (PMID 41225536, 2025). "Although FGD3 is highly expressed in breast cancer as a favorable prognostic marker, its function in the pathophysiology of breast cancer remains unclear." (PMID 41225536, 2025). "The TCGA database analysis does not suggest FGD3 level is correlated with metastasis status and one previous study showed low FGD3 level might increase lymph node metastasis in a cohort of 60 young breast cancer patients." (PMID 41225536, 2025). "Here, we explore the role of FGD3 in lytic cell death in breast cancer." (PMID 41225536, 2025). "Supporting clinical relevance, high FGD3 expression strongly correlated with improved relapse-free survival in breast cancer patients after chemotherapy and this correlation was stronger than was seen for NINJ1 and other proteins associated with lytic cell death." (PMID 41225536, 2025). "Therefore, FGD3’s role in the metastasis of different types of breast cancer remains controversial and requires future exploration." (PMID 41225536, 2025). "Our data suggest that inclusion of FGD3 evaluation in the routine workup of breast cancer patients may result in a more accurate stratification of the individual risk." (PMID 34359725, 2021).
breast carcinoma (continued). "In this series, however, the association between FGD3 staining intensity and involvement of more than 10 lymph nodes, that we found in a previous study limited to breast cancer in young women, was not confirmed." (PMID 34359725, 2021). "FGD3, a putative regulator of cell morphology and motility, was associated with longevity in the NECS study, and its expression plays a prognostic role in breast cancer." (PMID 33657282, 2021). "Interestingly, according to multivariate analysis, our results indicate that FGD3 expression represents an independent predictor of clinical outcome in breast cancer patients in terms of OS, second only to the AJCC stage, in agreement with the literature." (PMID 34359725, 2021). "Therefore, further studies on FGD3 in breast cancer are warranted to evaluate both its prognostic significance and to explore the possibility of modulating this gene expression for therapeutic purposes." (PMID 31645624, 2019). "Given the obvious cohort differences in treatment conditions, patient populations, formalin-fixed paraffin-embedded frozen tissue, and platform differences in Illumina and RNA-seq, FGD3 represents a robust indicator of outcome in breast cancer as well as other cancers and requires further study." (PMID 32913979, 2017). "Consequently, FGD3 level is strongly correlated with cancer cell sensitivity to ErSO-induced lytic cell death in 2-dimensional (2D) cell culture, 3-dimensional (3D) patient-derived breast cancer organoids (PDOs) and orthotopic mouse xenografts." (PMID 41225536, 2025). "The loss of FGD3 similarly prevented cell death but not decreased proliferation in more physiologically relevant models that better mimic the 3D tumor environment – 3D breast cancer cell organoids and orthotopic mouse xenografts." (PMID 41225536, 2025). "We therefore hypothesize that elevated FGD3 expression in breast cancers may be correlated with better patient outcomes because FGD3 both enhances NK cell-mediated cell lysis and increases the effectiveness of doxorubicin and other lytic cell death-inducing anticancer therapies." (PMID 41225536, 2025). "Notably, we demonstrate elevated FGD3 in breast cancer cells increases NK cell-mediated lysis." (PMID 41225536, 2025). "To explore the role of FGD3 in ErSO-induced lytic cell death, we began by producing MCF-7 and T47D human breast cancer cells in which FGD3 was knocked out or overexpressed." (PMID 41225536, 2025). "We identified FGD3 as a key mediator, coupling cell swelling to PMR and lytic cell death induced by emerging and current breast cancer therapies, including ErSO, aprepitant, doxorubicin and epirubicin." (PMID 41225536, 2025). "The most relevant finding of our study was the strong prognostic role of FGD3 expression as evaluated by IHC on both DFS and OS, in accordance with the few previous studies that pointed out its value in breast cancer patients." (PMID 34359725, 2021). "The FGD3 cell line experiment in this study and studies by others suggests that FGD3 mRNA expression is partially regulated by ESR1, an important treatment target in breast cancer, which requires further study." (PMID 32913979, 2017). "Comparing the prognostic value of FGD3 in breast cancer with the prognostic value of genes associated with proliferation such as MKI67, PCNA, and AURKA indicates that FGD3 may offer superior disease progression metrics in all clinically relevant breast cancer subtypes." (PMID 32913979, 2017). "Prognostic significance of faciogenital dysplasia 3 (FGD3), SUSD3, and other single-gene proliferation markers was evaluated in breast cancer and The Cancer Genome Atlas (TCGA) cohorts." (PMID 32913979, 2017). "Published ESR1 chromatin immunoprecipitation sequencing data in breast cancer cell lines MCF-727 and ZR-75-128 identified a conserved ESR1 binding site within the gene locus of FGD3." (PMID 32913979, 2017).
breast carcinoma (continued). "As a control, in the database of relapse-free survival in breast cancer patients receiving endocrine therapies, which do not typically induce lytic cell death, there was not a statistically strong correlation between FGD3 level and patient response." (PMID 41225536, 2025). "In addition, The Human Protein Atlas does not consider FGD3 expression as prognostic marker in breast cancer, whereas it reports that FGD3 has prognostic value in head and neck and cervical cancers." (PMID 34359725, 2021). "The potential of FGD3 as a biomarker for freedom from recurrence was evaluated in the Breast International Group 1-98 (BIG 1-98; Letrozole or Tamoxifen in Treating Postmenopausal Women With Breast Cancer) study (HR, 0.85; 95% CI, 0.76 to 0.93) for breast cancer–free interval." (PMID 32913979, 2017). "FGD3 mRNA expression as a biomarker for an immune response was evaluated by using tumor-infiltrating lymphocyte cells in TCGA breast cancer and Breast International Group 1-98 (BIG 1-98; Letrozole or Tamoxifen in Treating Postmenopausal Women With Breast Cancer) cohorts." (PMID 32913979, 2017). "The prognostic significance of FGD3 and SUSD3 as single gene prognostic biomarker using Cox regression models in a large collection of breast cancer cohorts and TCGA cohorts has not been published." (PMID 32913979, 2017). "FGD3 mRNA expression did not correlate with TILs in the BIG 1-98 DASL and TCGA breast cancer cohorts, suggesting that the prognostic value of FGD3 is not indicating immune cells in patients’ tumors." (PMID 32913979, 2017).
lymph node metastases (3 papers, 2017 to 2021). "An unpaired t test comparing N0 with N1 to N3 suggests that lymph node metastasis is associated with lower FGD3 protein levels (P < 1E-4)." (PMID 32913979, 2017). "We observed that patients with low levels of FGD3 expression had a higher incidence of lymph node metastases than those with higher levels of FGD3 expression (45.7% versus 27.6%), and the difference was significant (p < 0.001)." (PMID 34359725, 2021). "We found that low FGD3 expressing patients had higher incidence of lymph node metastases as compared with high FGD3 expressing ones, (61.9% versus 41.0%), but the difference was not significant (p = 0.12)." (PMID 31645624, 2019). "By using metadata provided by US Biomax, FGD3 protein levels in tumors (n = 135) with no regional lymph node metastasis (N0) were compared with tumors with lymph node metastasis (N1 to N3) and corresponding matched metastatic tissues." (PMID 32913979, 2017).
head and neck squamous cell carcinoma (2 papers, 2017 to 2023). A squamous cell carcinoma that arises from any of the following anatomic sites: lip and oral cavity, nasal cavity, paranasal sinuses, pharynx, larynx, and salivary glands. "FGD3 is uniquely highly prognostic in head and neck squamous cell carcinoma and lung adenocarcinoma." (PMID 32913979, 2017).
invasive breast carcinoma (2 papers, 2017 to 2021). A carcinoma that infiltrates the breast parenchyma. "The aim of the study was to evaluate the prognostic role of FGD3 in invasive breast cancer in a series of 401 women, treated at our unit, by evaluating the expression of this gene by immunohistochemistry." (PMID 34359725, 2021). "FGD3 is prognostic in breast invasive carcinoma, cervical squamous cell carcinoma, sarcoma, and bladder urothelial carcinoma." (PMID 32913979, 2017). "Stage IIA invasive breast cancer showed strong FGD3 expression compared with its matched metastatic carcinoma, in which FGD3 was weakly expressed." (PMID 32913979, 2017).
pancreatic cancer (2 papers, 2023 to 2025). "For instance, the interaction between FGD3 and HSF4 can inhibit the expression of p65, thereby suppressing pancreatic cancer progression." (PMID 39881364, 2025).
triple-negative breast carcinoma (2 papers, 2017 to 2021). An invasive breast carcinoma which is negative for expression of estrogen receptor (ER), progesterone receptor (PR), and human epidermal growth factor receptor 2 (HER2). "Among the patients with triple-negative breast cancer, in the present study FGD3 expression confirmed to influence survival; however, the difference was not significant, possibly because of the small sample size." (PMID 34359725, 2021). "Surprisingly, FGD3 mRNA expression in BT-20, a triple-negative breast cancer cell line, was upregulated to 1.99 and ESR1 was upregulated to 0.47 on a log2 scale when treated with an EGFR inhibitor." (PMID 32913979, 2017).
breast adenocarcinoma (1 paper, 2017). "Benign tumors and breast adenocarcinomas in lower stages showed strong expression of FGD3, whereas late-stage breast adenocarcinomas in higher stages showed mild to weak expression." (PMID 32913979, 2017).
cerebrovascular diseases (1 paper, 2024). "There were 6 genes related to cardiovascular and cerebrovascular diseases, which were Fgd3, Myoz3, AC095693.1, Adamts3, PDGFA and PDGFRα." (PMID 38195688, 2024).